KLF4 (KLF transcription factor 4)
Diseases named in the same sentence as KLF4 in open-access papers (continued):
Sharing a sentence is not in itself a finding about the gene and the disease.
nasopharyngeal carcinoma (continued). "Similar overexpression of KLF4 was also observed in various nasopharyngeal carcinoma cell lines." (PMID 30108202, 2018). "The current study found that the detection of KLF4 expression in the nucleus by IHC could predict whether the nasopharyngeal carcinoma was resistant to cetuximab based on the previous study." (PMID 29973197, 2018). "Evidence displayed the role of KLF4 in triggering EMT in non-small cell lung and endometrial cancers and human nasopharyngeal carcinoma." (PMID 36553636, 2022). "However, the clear mechanism by which KLF4 exerts in nasopharyngeal carcinoma remains unknown." (PMID 30108202, 2018). "Although loss of cytoplasmic Klf4 protein was frequently observed in the clinical tissue specimens of nasopharyngeal carcinoma (NPC), the functions of Klf4 in NPC is still unknown." (PMID 29212199, 2017). "Klf4 is dysregulated and displays divergent functions in multiple malignancies, but the biological roles of Klf4 in nasopharyngeal carcinoma (NPC) remain unknown." (PMID 29212199, 2017). "Importantly, our data demonstrate that the interaction of KLF4 and SOX2-induced expression of PI3K/AKT signaling is a critical mechanism for SOX2-driven nasopharyngeal carcinoma proliferation." (PMID 30108202, 2018). "The KLF4 expression in the nucleus was not significantly correlated with the prognosis in 63 nasopharyngeal carcinoma patients treated with basic treatment (P = 0.261)." (PMID 29973197, 2018). "Taken together, these results clearly indicated that KLF4 could directly binds to SOX2 and might serve as a oncogenic molecular prognostic marker for nasopharyngeal carcinoma." (PMID 30108202, 2018). "Since KLF4 can act as both a tumor enhancer and suppressor, we compared expression of KLF4 in tumor tissues with non-cancerous tissues to determine its exactly role in nasopharyngeal carcinoma." (PMID 30108202, 2018). "Furthermore, we successfully demonstrated that KLF4 serves as a oncogene and directly binds to SOX2 in nasopharyngeal carcinoma." (PMID 30108202, 2018). "The prognosis of nasopharyngeal carcinoma was not significantly improved by cetuximab treatment when the Klf4 was highly expressed in the nucleus of nasopharyngeal carcinoma tissues." (PMID 29973197, 2018). "In order to explore whether similar phenomenon exists in nasopharyngeal carcinoma, a protein–protein interaction network was built according to the STRING database, which exhibited that plenty of proteins interacts with SOX2 including KLF4." (PMID 30108202, 2018).
sarcoma (12 papers, 2015 to 2024). A usually aggressive malignant neoplasm of the soft tissue or bone. "We observed an increase in the Nanog, Nes, Oct4, Sox2, Klf4, and Myc mRNA levels in the mice with a functional allele of Emx(+/−) and especially in the null Emx(−/−), with higher levels in the induced sarcoma compared to the control muscle tissue." (PMID 34016958, 2021). "KLF4 has a role in chemoresistance in addition to promoting the formation of OS sarcoma spheres and the cancer stemness of OS cells." (PMID 38546623, 2024). "The expression of the tumor suppressor gene KLF4 in sarcoma cells is also increased, and its high expression leads to a high survival rate of patients." (PMID 34696664, 2022). "Coincidentally, both mTOR and KLF4 are target genes of hsa-mir-7-5p and hsa-mir-145-5p, and both are also aberrantly highly expressed in sarcoma." (PMID 34696664, 2022). "NANOG is important for CSC maintenance, as it regulates the expression of other stem cell markers OCT4, SOX2, KLF4, and promotes sarcoma CSC features such as spheroid formation, anchorage-independent growth, migration and invasion." (PMID 35145908, 2021). "Comparing the control muscle tissues and the induced sarcoma, we observed the highest expression of the stem cell genes (Oct4, Sox2, Klf4, Myc, and Nanog) and aggresivity in the sarcomas induced in the Emx1 or Emx2 KO mice." (PMID 34016958, 2021). "Our data additionally demonstrates that Oct4, Nanog, Sox2, Klf4, and Myc are widely expressed at high levels across a wide variety of sarcomas and benign vascular tumors at elevated levels." (PMID 26412983, 2015). "Box and whisker plots depicting the IHC scores for Oct4, Nanog, Myc, Sox2, and Klf4 in normal vasculature, benign, borderline or malignant vascular tumors, or across a panel of various sarcomas." (PMID 26412983, 2015). "Another study from that year also confirmed that KLF4 expression rose in sarcomas." (PMID 38546623, 2024). "Survival analysis revealed that higher expression of SOX2, NANOG, and MYC but not OCT4 (POU5F1) or KLF4 is associated with significantly reduced survival in sarcoma patients." (PMID 36506091, 2022). "With the expression of pluripotency factors such as OCT3/4, NANOG, KLF4 and SOX2, stemness in sarcoma is a variable condition." (PMID 37635229, 2023). "Our work showed that EMX1/EMX2 act as tumor suppressors in sarcomas by repressing the activity of stem cell regulatory genes (OCT4, SOX2, KLF4, MYC, NANOG, NES, and PROM1)." (PMID 34016958, 2021). "In summary, our work showed that EMX1 and EMX2 act as tumor suppressors by suppressing the activity of stem cell regulatory genes (OCT4, KLF4, MYC, SOX2, NANOG, NES, and PROM1) in sarcoma." (PMID 34016958, 2021). "The stemness state in sarcomas is orchestrated by the expression of pluripotency factors such as OCT3/4, NANOG, KLF4, and SOX2." (PMID 32295077, 2020). "FOXM1 stimulates transcription of pluripotency related genes including SOX2, KLF4, OCT4, and NANOG many of which are important in sarcoma, a disorder of mesenchymal stem cell/ partially committed progenitor cells." (PMID 27074562, 2016). "We analyzed the expression of the stemness genes c-Myc, KLF4, Nanog, and OCT3/4 that were previously normalized to ACTB, with the identified top-ranking HKG for CSC and native cells, in sarcoma and carcinoma, respectively (GAPDH and YWHAZ for sarcoma, and PPIA and HMBS for carcinoma)." (PMID 26894994, 2016). "KLF4 is a tumor suppressor gene, and mTOR is a proto-oncogene, so we speculate that overexpressed mTOR is not conducive to the prognosis of patients with sarcoma; the effect of KLF4 should be just the opposite." (PMID 34696664, 2022). "In addition, the tumor suppressor gene KLF4 is overexpressed in sarcoma, which should be a negative feedback regulation of cell proliferation." (PMID 34696664, 2022).
sarcoma (continued). "While Klf4 protein expression was not significantly different between any of the vascular tumors or vascular tissue controls, this protein did show a significantly increased mean IHC score in the sarcoma tissue control set." (PMID 26412983, 2015).
acute lymphoblastic leukemia (11 papers, 2014 to 2026). Leukemia with an acute onset, characterized by the presence of lymphoblasts in the bone marrow and the peripheral blood. "During the last decade, significant progress has been made in understanding the role of KLF4 in the pathogenesis of T‐cell acute lymphoblastic leukemia (T‐ALL)." (PMID 41532367, 2026). "In T‐cell acute lymphoblastic leukemia (T‐ALL), KLF4 expression is silenced by promoter methylation, and the induction of KLF4 suppresses the proliferation of T‐ALL cells." (PMID 40354086, 2025). "Epigenetic silencing has been also demonstrated in T-cell acute lymphoblastic leukemia (T-ALL), where KLF4 serves as tumor suppressor in experimental animal models and xenografts generated using lymphoblasts from pediatric T-ALL patients." (PMID 39135777, 2024). "Inducible KLF4-overexpression Jurkat cell line combined with mouse models bearing cell-derived xenografts and primary T-cell acute lymphoblastic leukemia (T-ALL) cells from four patients were used to assess the functional role of KLF4 in T-ALL cells in vitro and in vivo." (PMID 25644173, 2015). "In addition to its well-known functions in lymphoblastic leukaemia and a number of cancers, PBX1 was also found to promote hESC self-renewal by corporately binding to the regulatory elements of NANOG with KLF4." (PMID 30217220, 2018). "Additionally, some studies have shown that KLF4 inhibits MAP2K7, and its deletion can activate MAP2K7 in T-cell acute lymphoblastic leukemia (ALL)." (PMID 40406144, 2025).
endothelial dysfunction (11 papers, 2017 to 2025). In vascular diseases, endothelial dysfunction is a systemic pathological state of the endothelium (the inner lining of blood vessels) and can be broadly defined as an imbalance between vasodilating and vasoconstricting substances produced by (or acting on) the endothelium. "Similarly, the overexpression of DNMT3a and DNMT3b causes hypermethylation of the CREG and KLF4 promoters, suppressing their expression and promoting endothelial dysfunction." (PMID 40428388, 2025). "Thus, the loss of Klf4 in quiescent ECs is primarily responsible for endothelial dysfunction, vascular leakage, and EndMT, and secondarily promotes neutrophil and macrophage recruitment in the lung that gave rise to alveolar enlargement and fibrosis." (PMID 36425528, 2022). "The flow-responsive transcription factors KLF2 and KLF4 play an important role in restricting endothelial dysfunction, inflammation, thrombosis, and angiogenesis in response to disturbed flow." (PMID 40362576, 2025). "The suppression of protective endothelium genes, specifically KLF2 and KLF4, through targeted targeting has revealed the critical role of miR-92a-3p as a regulator of angiogenesis and endothelial dysfunction." (PMID 38074330, 2023). "Prior studies have shown that NEAT1 promotes endothelial pyroptosis and vascular inflammation through KLF4/NLRP3 signaling, and that exercise downregulates NEAT1 to attenuate endothelial dysfunction in AS." (PMID 41268533, 2025).
head and neck cancer (11 papers, 2015 to 2023). A primary or metastatic malignant neoplasm affecting the head and neck. "Increased KLF4 nuclear expression has been associated with poor prognosis in patients with breast and head and neck cancer." (PMID 37559082, 2023). "Moreover, high expression of KLF4 is associated with prolonged OS in GC, BC and head and neck cancer and may be a predictive factor for these cancers." (PMID 35177016, 2022). "KLF4 has also been shown to play a role in the transdifferentiation of head and neck cancer cell lines into endothelial cells." (PMID 37762678, 2023). "In head and neck cancer the regulation of KLF4 gene expression was further influenced by human papilloma virus." (PMID 35219646, 2022). "It has been suggested that KLF4 expression can be used as a poor prognostic factor in head and neck cancer." (PMID 32733958, 2020). "Immunohistochemistry staining of Twist1, Jagged1, and KLF4 in 242 head and neck cancer patient samples showed there was significant correlation between Twist1, Jagged1, and KLF4." (PMID 26823670, 2016). "Additionally, radiotherapy induced the dedifferentiation of head and neck cancer cells into stem cells and increased plasticity by Yamanaka reprogramming factors (transcription factors Oct4 (Pou5f1), Sox2, cMyc and Klf4) in HPV-negative cell lines." (PMID 30875950, 2019). "Furthermore, we also examined the correlation between the expression of Twist1, Jagged1, and KLF4 in head and neck cancer patient samples." (PMID 26823670, 2016). "To investigate the relationships between EMT, CSCs and TRAF6 in head and neck cancer, we discovered that the expression of TRAF6 in SCCHN was significantly correlated with EMT markers (i.e. Vimentin and Slug) and CSC markers (i.e. CD44, KLF4, ALDH1 and SOX2)." (PMID 29193723, 2018).
myeloid leukemia (11 papers, 2014 to 2025). A clonal proliferation of myeloid cells and their precursors in the bone marrow, peripheral blood, and spleen. "This study also found that patients with lower HDAC1 and higher Klf4 levels had better prognosis, making these proteins new potential diagnostic and prognostic markers and therapy targets for myeloid leukemia." (PMID 25341045, 2014). "In myeloid leukemias, KLF4 has pro-leukemic function in CML by suppressing a mechanism that inhibits LSC self-renewal, and in AML by promoting the expansion of LSCs." (PMID 40589762, 2025). "HDAC1 and KLF4 interact with each other to regulate the proliferation of human myeloid leukemia cells." (PMID 36211454, 2022). "After a full-length complementary DNA or an antisense oligonucleotide of KLF4 was transfected into a human immortalized myelogenous leukemia line (K562 cells), cell growth was decreased and cell apoptosis was increased." (PMID 29848383, 2018). "Further functional and mechanistic studies indicated that HDAC1 specifically targets Klf4 and that this interplay inhibits myeloid leukemia cell proliferation and cell cycle." (PMID 25341045, 2014). "Further studies suggested that the mechanism by which HDAC1 affects myeloid leukemia cells is mainly by regulating Klf4." (PMID 25341045, 2014). "Mechanistic analyses demonstrated that HDAC1 and Klf4 competitively bound to the promoter region of Klf4 and oppositely regulated Klf4 expression in myeloid leukemia." (PMID 25341045, 2014). "In this review article, part of the research topic “Exploring KLF4’s role in immune cell function and disease progression,” we will summarize KLF4’s role in blood cells, including immune cells, and focus on hematological malignancies, mainly lymphoid and myeloid leukemias." (PMID 40589762, 2025). "By evaluating the effects of specific HDACs in human myeloid leukemia, we first found that the expression level of HDAC1 was negatively correlated with Klf4 expression and that patients with lower HDAC1 levels showed a better prognosis." (PMID 25341045, 2014). "Furthermore, reactivation of KLF4 expression through modulation of PPARγ signaling, exerted a multifaceted tumor-suppressive effect in CDX2 positive myeloid leukemia cell lines and primary AML blasts, suggesting PPARγ agonists as a therapeutic modality in a large proportion of AML patients." (PMID 30542286, 2018). "In contrast, KLF4 overexpression did not induce apoptosis either in RL, a B cell lymphoma cell line, or in K562, a myeloid leukemia cell line." (PMID 25644173, 2015).
seminoma (11 papers, 2016 to 2023). A radiosensitive malignant germ cell tumor found in the testis (especially undescended), and extragonadal sites (anterior mediastinum and pineal gland). "This is the first identification of a cell population in seminoma characterized for being OCT4, KLF4, and PTTG1 positive cells in seminoma, associated with cancer invasiveness." (PMID 31572301, 2019). "This pilot study provides the first identification of a cell population in seminoma characterized for being OCT4, KLF4, and PTTG1 positive cells in seminoma, associated with cancer invasiveness." (PMID 31572301, 2019). "KLF4, overexpressed in seminoma cells, prevents differentiation and maintains proliferation and pluripotency during germ cell tumorigenesis; therefore, KLF4 may be vital in the neoplastic transformation of testicular stem cells." (PMID 33777092, 2021). "Preliminary reports demonstrated that most cells in seminoma express Pituitary-tumor-transforming-gene 1 (PTTG1), as well as Octamer-binding transcription factor 4 (OCT-4) and Krüppel-like factor 4 (KLF-4)." (PMID 34209730, 2021). "In this pilot study, we compared the combined expression of PTTG1 with KLF4 and OCT4 in seminoma, in order to validate our hypotesis that PTTG1 marks a specific population of stem cells in neoplastic tissue, strictly related with tumor." (PMID 31572301, 2019). "In this study we confirmed that some cells in seminoma express PTTG1 and demonstrated that it is a sub-population of tumor stem cells OCT4- and KLF4- positive cells." (PMID 31572301, 2019). "In this pilot study, we compared the combined expression of PTTG1 with KLF4 and OCT4 in seminoma, in order to validate our hypothesis that PTTG1 could mark a specific subset of neoplastic stem cells, strictly related with tumor." (PMID 31572301, 2019). "Formalin-fixed and paraffin-embedded testicular tissues by 5 patients who underwent an orchidectomy for seminoma have been collected and immunofluorescence analysis was performed using antibody rabbit monoclonal PTTG-1 and mouse monoclonal OCT4 or mouse monoclonal KLF4 antibody." (PMID 31572301, 2019).
triple-negative breast carcinoma (11 papers, 2015 to 2025). An invasive breast carcinoma which is negative for expression of estrogen receptor (ER), progesterone receptor (PR), and human epidermal growth factor receptor 2 (HER2). "In most highly malignant triple-negative breast cancers, KLF4 prevents tumor proliferation, migration, and invasion, and is a biomarker of benign prognosis." (PMID 37031197, 2023). "Small molecule inhibitors WX2-43 and MM-102 also inhibited KLF4 methylation and destabilized KLF4 by acting on methyltransferases to inhibit the progression of triple-negative breast cancer." (PMID 37031197, 2023). "However, in the highly malignant triple-negative breast cancer, high expression of KLF4 inhibits cancer cells proliferation and invasion, and KLF4 is also a marker of prognosis in triple-negative breast cancer." (PMID 37031197, 2023). "PARylation of KLF4 may be involved in oncogenic signaling, and PARPis could be alternatively used for the treatment of triple-negative breast cancers." (PMID 36077221, 2022). "Similar to TTP, ZFP36L1 phosphorylation and inactivation by the p38–MK2 axis has been shown to stabilize Nanog and Klf4 in triple-negative breast cancer cells, resulting in breast cancer stem cell phenotype, a feature of chemotherapy-resistance in triple-negative breast cancer." (PMID 32545247, 2020). "For instance, in triple-negative breast cancer, the small molecule inhibitor WX2-43 blocks KLF4 methylation by inhibiting the Protein Arginine Methyltransferase 5 (PRMT5) -KLF4 interaction, showing significant antitumor efficacy." (PMID 39995670, 2025). "This study reveals a novel role for KLF4 PARylation in DNA damage response in cancer, and reports a synergy between targeting KLF4 and PARP1 in the treatment of triple negative breast cancer (TNBC)." (PMID 33231937, 2020). "KLF4 promotes RAS-extracellular signal-regulated kinase pathway activity and tumor cell survival in triple-negative breast cancer (TNBC) cells." (PMID 26053033, 2015).
Alzheimer disease (10 papers, 2018 to 2025). A progressive, neurodegenerative disease characterized by loss of function and death of nerve cells in several areas of the brain leading to loss of cognitive function such as memory and language. "Several studies indicate that KLF4 is linked to multiple neurological disorders, including Alzheimer’s disease (AD), epilepsy, Parkinson’s disease, hydrocephalus and schizophrenia." (PMID 30297986, 2018). "Furthermore, previous studies have demonstrated that upregulation of KLF4 significantly exacerbates neuroinflammation induced by amyloid-β, a major hallmark of Alzheimer’s disease." (PMID 40471885, 2025). "Moreover, several studies indicate that KLF4 is linked to multiple neurological disorders, including Alzheimer’s disease." (PMID 32545722, 2020). "Klf4 regulates amyloid-β (Aβ)-induced neuroinflammation and plays a potential role in not only oligomeric Aβ42-induced neurotoxicity but also the pathogenesis of Alzheimer's disease." (PMID 32035423, 2020). "Emerging evidence suggest KLF4’s critical regulatory effect on the neurophysiological and neuropathological processes of Alzheimer’s disease (AD), indicating that KLF4 might be a potential therapeutic target of neurodegenerative diseases." (PMID 30297986, 2018). "Importantly, Klf4 contributes to microglia‐mediated neuroinflammation in Alzheimer's disease." (PMID 39234952, 2024). "In addition, KLF4 was uncovered to be relevant to the pathogenesis of Alzheimer’s disease." (PMID 33071725, 2020).